SLC26A7 (solute carrier family 26 member 7)
Description:
Acts as an anion channel mediating the transport of chloride, sulfate and oxalate ions. Mediates the transport of bromide, iodide, nitrate, gluconate, thiocyanate and bicarbonate ions (By similarity). Its permeability towards bicarbonate is weak and increases when pH is above 7 (By similarity). Mediates thiocyanate transport in retinal pigment epithelium cells (By similarity). Mediates iodide transport in the thyroid gland, playing an important role in the synthesis of thyroid hormones and the maintenance of thyroid function. Although it is an anion channel, according to PubMed:12736153 and PubMed:32119864 it has been shown to exhibit chloride-bicarbonate exchanger activity.
Synonyms: SUT2
Tractability: Antibody: UniProt places it where antibodies can reach, with high confidence; its Gene Ontology location is reachable by antibodies, with high confidence; UniProt predicts a signal peptide or a membrane-spanning region.
Gene: Protein-coding gene on chromosome 8 (91,209,494 to 91,398,155, forward strand). Ensembl gene ENSG00000147606.
Subcellular location: Cell membrane; Basolateral cell membrane; Recycling endosome membrane; Apical cell membrane; Lateral cell membrane
Subcellular location (Human Protein Atlas): Vesicles; Golgi apparatus; Mid piece; Perinuclear theca
Pathways (Reactome):
Transport of small molecules: Inorganic anion exchange by SLC26 transporters
Gene Ontology:
Molecular function: chloride channel activity; chloride:bicarbonate antiporter activity; oxalate transmembrane transporter activity; sulfate transmembrane transporter activity; bicarbonate transmembrane transporter activity; monoatomic anion channel activity
Biological process: chloride transport; iodide transport; oxalate transport; sulfate transmembrane transport; bicarbonate transport; chloride transmembrane transport; transmembrane transport; carboxylic acid transmembrane transport; gastric acid secretion; gluconate transmembrane transport; nitrate transmembrane transport; thyroid hormone generation
Cellular component: apical plasma membrane; basolateral plasma membrane; cytoplasm; endosome; lateral plasma membrane; plasma membrane; recycling endosome membrane; membrane
Genetic constraint (gnomAD): Loss-of-function variants: 40 observed, 50.69 expected, observed/expected ratio (o/e) 0.79, 90% interval 0.61 to 1.03. The upper end of that interval is the gene's LOEUF score, 1.03, which puts it in group 4 of 6, group 1 being the genes least tolerant of losing a copy. Missense variants: 632 observed, 630.4 expected, observed/expected ratio (o/e) 1, 90% interval 0.94 to 1.07. Synonymous variants: 208 observed, 228.36 expected, observed/expected ratio (o/e) 0.91, 90% interval 0.81 to 1.02.
Homologues: Orthologues: chimpanzee SLC26A7 (98% identical), macaque SLC26A7 (97% identical), pig SLC26A7 (91% identical), dog SLC26A7 (91% identical), guinea pig SLC26A7 (88% identical), mouse Slc26a7 (88% identical), rat Slc26a7 (86% identical), rabbit SLC26A7 (81% identical), tropical clawed frog slc26a7 (54% identical), Caenorhabditis elegans sulp-3 (30% identical), Caenorhabditis elegans sulp-5 (29% identical), Caenorhabditis elegans sulp-4 (29% identical), and 5 more. Paralogues in human: SLC26A3 (32% identical), SLC26A4 (31% identical), SLC26A2 (31% identical), SLC26A5 (29% identical), SLC26A6 (29% identical), SLC26A9 (27% identical), SLC26A1 (27% identical), SLC26A8 (25% identical), SLC26A11 (20% identical).
Diseases named in the same sentence as SLC26A7 in open-access papers:
SLC26A7 is named in the same sentence as 23 diseases in open-access papers, as found by Europe PMC text mining. Sharing a sentence is not in itself a finding about the gene and the disease. The quoted sentences say what the papers report.
congenital hypothyroidism (4 papers, 2019 to 2023). A thyroid hormone deficiency present from birth. "SLC26A7 encodes an anion transporter and mutations in the SLC26A7 protein were found in individuals with congenital hypothyroidism, though the role of this gene in brain structure is unclear." (PMID 37254169, 2023). "Previously, we reported that SLC26A7 is also involved in iodide transport and that Slc26a7 is a novel causative gene for congenital hypothyroidism." (PMID 35788623, 2022). "We also discovered a homozygous nonsense mutation in SLC26A7 in two Japanese siblings with congenital hypothyroidism; the mutation abolished membrane localisation and the iodide transport function of SLC26A7." (PMID 31372509, 2019). "They identify a nonsense mutation in SLC26A7 in siblings with congenital hypothyroidism and goitre using whole-exome sequencing, implicating this transporter in disease." (PMID 31372509, 2019). "Furthermore, because the clinical features are masked by the administration of thyroid hormones, patients with a mutation in SLC26A7 are likely undiagnosed patients with congenital hypothyroidism." (PMID 31372509, 2019). "Third, because there is a paucity of clinical information on congenital hypothyroidism caused by loss of function of SLC26A7, we do not believe that these results in mice are entirely consistent with the human phenotype." (PMID 35788623, 2022).
thyroid (3 papers, 2021 to 2024). "Remarkably, SLC26A7 was found to be expressed in both gastric and thyroid tissues and recently, alterations in SLC26A7 were reported associated with in thyroid diseases, such thyroid dyshormonogenesis, congenital goitrous hypothyroidism and primary anaplastic thyroid cancer." (PMID 34944008, 2021). "Cotransporter genes involved in achlorhydria (SLC26A7, SLC26A9 and ATP4A) were also strongly associated with thyroid disease in thyrogastric patients, suggesting a monogenic model for the thyrogastric syndrome." (PMID 34944008, 2021). "Generally, various genetic and molecular studies addressed the issue of congenital hypothyroidism (for example, anomalies of TSHR, SLC26A7, JAG1, DUOX2, and FOXE1 gene) linking the thyroid dyshormonogenesis to thyroid dysgenesis." (PMID 38791947, 2024).
dyshormonogenesis (2 papers, 2021). "Recently, it has been identified that loss-of-function variants in SLC26A7 are another genetic cause of dyshormonogenesis." (PMID 34200080, 2021).
hypothyroidism (2 papers, 2019 to 2022). Abnormally low levels of thyroid hormone. "Second, we could not investigate the pathophysiological mechanism by which functional Slc26a7 deficiency causes goitrous hypothyroidism." (PMID 35788623, 2022). "Thus, Slc26a4 (−/−) mice displaying iodide deficiency are euthyroid, while Slc26a7 (−/−) mice show hypothyroidism with histological thyroid abnormalities." (PMID 31372509, 2019). "In addition, the patients that presented with the SLC26A7 mutation showed severe hypothyroidism, even though in Japan, dietary iodide is sufficient." (PMID 31372509, 2019). "In addition, Slc26a7 knockout mice displayed hypothyroidism with histological observations of hyperplastic thyrotrophs." (PMID 31372509, 2019).
anaplastic carcinoma (1 paper, 2024). "There is evidence that decreased SLC26A7 expression accompanies the development of anaplastic carcinoma and significantly correlates with a poor prognosis among the patients, whereas in PTC, SLC26A7 downregulation has been associated with an elevated risk of metastases outside the thyroid." (PMID 39682560, 2024).
COVID-19 (1 paper, 2025). A disease caused by infection with severe acute respiratory syndrome coronavirus 2. "Consequently, the research pinpointed four key genes, MBP, CYP4B1, ERMN, and SLC26A7, which hold clinical relevance and exhibit potential significance in the pathophysiology of COVID-19 induced depression." (PMID 40918512, 2025).
gastric disease (1 paper, 2021). "Importantly, KO mouse models for SLC26A7, SLC26A9, and SLC4A2 were described with gastric achlorhydria, which demonstrates that alterations found in our patients might explain gastric disease." (PMID 34944008, 2021).
Hyperoxaluria (1 paper, 2023). Increased excretion of oxalates in the urine. "Both hyperoxaluric and non-hyperoxaluric patients were screened for sequence variations in known and candidate genes implicated in hyperoxaluria (AGXT, GRHPR, HOGA1, SLC26A1, SLC26A6, SLC26A7) by targeted next generation sequencing (tNGS)." (PMID 37270618, 2023). "To evaluate the contribution of genetic factors in the development of hyperoxaluria after bariatric surgery, we conducted tNGS to detect variations within genes known to cause monogenic hyperoxaluria and Ca-Ox-NL (AGXT, GRHPR, HOGA1; SLC26A1) as well as the candidate genes SLC26A6 and SLC26A7." (PMID 37270618, 2023).
metastatic tumors (1 paper, 2025). "In metastatic tumors, significant reductions were observed in DIO1 activity (11-fold), TFF3 gene expression (8-fold), TPO expression (4-fold), and SLC26A7 expression (2.6-fold)." (PMID 40650194, 2025).
Pendred syndrome (1 paper, 2019). Pendred syndrome (PDS) is a clinically variable genetic disorder characterized by bilateral sensorineural hearing loss and euthyroid goiter. "However, about 50% of patients with Pendred syndrome are euthyroid, suggesting that SLC26A7 or another iodide transporter may compensate for the dysfunction of pendrin (SLC26A4)." (PMID 31372509, 2019).
thyroid cancer (1 paper, 2020). "Among the four methylation-driven genes, the high expression level of TREM1, BIRC7, and SLC26A7 prognosticated low survival rate, whereas RDH5 acted as protective genes to suggest good prognosis of thyroid cancer." (PMID 32296463, 2020).
SLC26A7 also shares sentences with these, for which no sentence is quoted: anaplastic thyroid carcinoma (1 paper); cancer (1); collecting duct carcinoma (1); depression (1); Gastric Neuroendocrine Tumors (1); Hydroureter (1); kidney (1); Kidney Cyst (1); Papillary Thyroid Carcinoma (1); polycystic kidney (1); renal cell carcinoma (1); tumour (1).